TRPM8 (transient receptor potential cation channel subfamily M member 8)
Diseases named in the same sentence as TRPM8 in open-access papers (continued):
Sharing a sentence is not in itself a finding about the gene and the disease.
melanoma (continued). "TRPM8 channels are overexpressed in a number of tumors, like prostate, melanoma, lung and colon adenocarcinomes, and some TRPM8 antagonists demonstrated good antitumor activity." (PMID 32843690, 2020). "In contrast, TRPM8 activation by menthol (a natural ligand for TRPM8) reduced survival of melanoma cells, suggesting its anticancer role in melanoma." (PMID 32575381, 2020). "In the present study, six thermo-TRPs including TRPV1/2/3/4, TRPA1, and TRPM8 were examined in human primary melanocytes and melanoma cells." (PMID 30881453, 2019). "We found that TRPV2/4, TRPA1, and TRPM8 exhibited ectopic distribution both in melanocytes and melanoma cells." (PMID 30881453, 2019). "In the present study, six thermo-TRPs including four heat sensors of TRPV1/2/3/4 and two cold sensors of TRPA1 and TRPM8 have been investigated among human melanocytes and melanoma cells." (PMID 30881453, 2019). "TRPM8 expression has been observed in human melanoma cells, where its activation results in elevations in intracellular calcium and reduced cell viability." (PMID 27983625, 2016). "Melanoma cells also express functional TRPM8 channels that produce a sustainable Ca2+ influx upon activation by menthol as agonist." (PMID 25710007, 2015). "TRPM8 targeting in combination with immunotherapy might be, hence, further explored in clinical setting of advanced melanoma." (PMID 41688418, 2026). "Our study identifies TRPM8 as a promising biomarker in melanoma." (PMID 41688418, 2026). "Additionally, TRPM8 modulators increase expression of the NK cell-activating ligand ULBP1, enhancing melanoma susceptibility to NK-mediated cytotoxicity." (PMID 41688418, 2026). "Similarly, the blockade of TRPM8, a cold-sensitive calcium channel, has been reported to inhibit melanoma cell migration and enhance sensitivity to chemotherapy, likely through modulation of calcium-dependent survival pathways." (PMID 40869148, 2025). "Indeed, our results show that Xenopus melanophores express multiple and similar TRP channels, including Trpm8,15 Trpa1, Trpv1, Trpv2, and Trpv4, to those detected in mammalian melanocytes and melanoma cells." (PMID 40978134, 2025). "Further, TRPM8 has been reported to participate in mediating agonist-induced melanoma cell death." (PMID 30881453, 2019). "We compare here the effects of TRPM8 activation on VEGF-induced transactivation of TRPV1 in an UM cell line (92.1) with those in normal primary porcine melanocytes (PM) since TRPM8 is upregulated in melanoma." (PMID 30483120, 2018). "However, activation of TRPM8 exerts an inhibitory role in melanoma." (PMID 31519770, 2019). "Therefore, TRPM8 channels play a role in melanoma proliferation." (PMID 29875336, 2018). "This review highlights the physiological expression of key TRP subfamilies (TRPM1, TRPM7, TRPM8, TRPV1, TRPV4, and TRPM2) in melanocytes and discusses their dysregulation in melanoma cells." (PMID 40869148, 2025). "Altered expression patterns and functional changes in TRPM1, TRPM7, TRPM8, TRPV1, and TRPV4 have notably been found to modulate cell survival, apoptosis, proliferation, and migration in melanoma models." (PMID 40869148, 2025). "TRPM2, TRPM8, TRPV1, and TRPV2 have been identified in melanoma cell lines, where their expression and function confer susceptibility to apoptosis and necrosis." (PMID 34831352, 2021). "Recent studies have reported that TRPM8 and TRPA1 exhibit abnormal expression in melanoma cell lines, and functional TRPV1, TRPM8, and TRPA1 have been found in malignant uveal melanoma tissues and cell lines." (PMID 34831352, 2021). "TRPM8 and TRPA1 channel proteins have been identified to exhibit abnormal expression in melanoma cell lines." (PMID 30881453, 2019).
pancreatic cancer (24 papers, 2012 to 2025). "ERK1/ERK2 and associated pathways have been reported to be modulated by TRPM8 expression in bone cancer, bladder cancer, pancreatic cancer and glioblastoma." (PMID 37033630, 2023). "Dysfunction of TRPM8 is associated with human pancreatic cancer and several other diseases in clinical patients, but the underlying mechanisms are unclear." (PMID 35665750, 2022). "When TRPM8 is deficient in pancreatic cancer cells, a reduced ability of proliferation and cell cycle progression with elevated levels of cyclin-dependent kinase inhibitors is observed." (PMID 29875336, 2018). "Knockdown of the genes encoding TRPM7 and TRPM8 induces senescence in pancreatic cancer cells." (PMID 35406743, 2022). "Models predicting the prognosis of patients with PDA utilizing TRPM8 and related genes have been constructed, underscoring TRPM8’s pivotal pathogenic role in pancreatic tumors and its potential utility as molecular biomarkers and therapeutic targets in pancreatic cancer." (PMID 39062591, 2024). "In addition, high TRPM8 protein expression was found to be associated with lower overall survival and poor disease free survival values for pancreatic cancer patients, as well as positively correlated with the tumor size and stage of pancreatic cancer." (PMID 32182937, 2020). "TRPM8 expression level in pancreatic cancer tissue has been found to be moderate to high (related to the stage of pancreatic cancer), and depends on the distance of metastasis and tumor size." (PMID 39150496, 2024). "Silencing TRPM8 through short hairpin RNA in pancreatic cancer cell lines with heightened TRPM8 levels has been shown to hinder invasive capabilities." (PMID 39062591, 2024). "Another study also reported abnormal TRPM8 expression in pancreatic cancer tissues that spur cancer by promoting cell cycle progression and impeding cancer cell replicative senescence." (PMID 39062591, 2024). "TRPM8 and TCAF2 expression levels in pancreatic cancer cells have been associated with cancer invasiveness, metastasis, and tumoral stage." (PMID 37033630, 2023). "On the contrary, TRPM8 expression decreases pancreatic cancer cell sensitivity to the chemotherapeutic gemcitabine, which is associated with changes in the expression of proteins responsible for multidrug resistance, apoptosis, and gemcitabine metabolism." (PMID 37033630, 2023). "In vivo assays in a mice PANC-1 cell-derived xenograft model of pancreatic tumors, expressing the control vector, WT, and Y1022F-TRPM8, showed up-regulated TRPM8 mRNA expression in tumors expressing WT or Y1022F." (PMID 36844925, 2022). "Elevated expression of TRPM8 has been found in human pancreatic cancer and several other diseases in clinical patients." (PMID 35665750, 2022). "Identification of the mechanisms by which TRPM8 mediates its biological functions is expected to develop into a molecular biomarker and therapeutic target in pancreatic cancer." (PMID 35665750, 2022). "In contrast, TRPM7 and TRPM8 abundances are elevated in pancreatic cancer where they play roles in the amelioration of OIS and replicative senescence." (PMID 35406743, 2022). "TRPM8, which is over-expressed in human pancreatic cancer cell lines, has been found to be required for the proliferation and invasion of pancreatic cancer cells and is closely linked to the sensitivity of gemcitabine, a pancreatic cancer chemotherapy drug." (PMID 36371178, 2022). "TRPM8 is overexpressed in pancreatic cancer cells and influences on the proliferation and migration ability of pancreatic cancer cells." (PMID 35813831, 2022). "TRPM8 regulation by LCK, a crucial lymphocyte-specific tyrosine kinase in regulating T-cell functions, reveals that the phosphorylation at Y1022 of the TRPM8 protein is important for pancreatic tumor cell proliferation, migration, and tumorigenesis." (PMID 36844925, 2022).
pancreatic cancer (continued). "Next, we used UCSC Xena to explore the expression levels of TRPV6, TRPA1, TCAF1, TCAF2, and TRPM8 in pancreatic cancer (n = 178) and in normal pancreatic tissue (n = 167)." (PMID 36012311, 2022). "Together, these data suggest that TRPM8 phosphorylation at Y1022 is critical for pancreatic cancer cell migration." (PMID 35665750, 2022). "Recently, several studies revealed that TRPM8 exhibits aberrant expression and contributes to the development and progression of pancreatic cancer." (PMID 35665750, 2022). "One example of a possible targeted therapy in the silencing of TRPM8, which enhances the effects of gemcitabine in vitro, in pancreatic cancer cell lines." (PMID 33925979, 2021). "In 2010, much like TRPM7 and TRPM2, TRPM8 was reported to be overexpressed in pancreatic cancer cell lines (PANC-1 and BxPC-3) when compared to pancreatic ductal epithelia." (PMID 33925979, 2021). "TRPM2 and 7 are overexpressed in humans while TRPM8 is reported overexpressed in pancreatic cancer cell lines." (PMID 33925979, 2021). "TRPM8 channels are also expressed and upregulated in some tumors including breast, lung and pancreatic carcinoma as well as glioblastoma, retinoblastoma and uveal melanoma cells." (PMID 33614639, 2021). "Other studies further confirmed the upregulation of TRPM8 in pancreatic cancer tissues in human patients compared to adjacent tissues." (PMID 32182937, 2020). "The expression pattern and levels of TRPM8 in pre-malignant pancreatic tissues and various subtypes of pancreatic neoplasms have been investigated." (PMID 26512697, 2015). "Consistent with its proliferative role, pancreatic cancer cells transfected with anti-TRPM8 siRNA exhibited impairment of cell cycle progression." (PMID 26512697, 2015). "We have discovered the regulatory roles of the zebrafish ortholog of mammalian TRPM7 in development of exocrine pancreas, and we subsequently identified the expression and functions TRPM7 and TRPM8 in human pancreatic cancer." (PMID 25770184, 2015). "Consistent with the proliferative role of TRPM8, pancreatic cancer cells with down-regulated expression of TRPM8 exhibited features of replicative senescence." (PMID 26512697, 2015). "In this study, we examined the expression of TRPM8 in human pancreatic tissues by immunohistochemistry and investigated its role in pancreatic cancer cells invasion." (PMID 24861976, 2014). "Results of this study suggest that aberrantly expressed TRPM8 channels play contributory roles in pancreatic tumor growth and metastasis." (PMID 24861976, 2014). "TRPM8 channels are required for maintaining proliferation and preventing replicative senescence of pancreatic cancer cells." (PMID 24861976, 2014). "Expression of TRPM8 in various types of histopathology in pancreatic tumors with regard to the intensity of immunoreactivity and the percentage of positive cells." (PMID 24861976, 2014). "TRPM8 is aberrantly expressed in chronic pancreatitis and PanINs, and various types of pancreatic tumors." (PMID 24861976, 2014). "SiRNA-mediated silencing of TRPM8 in pancreatic cancer cells reduced their ability to proliferate and progress through the cell cycle." (PMID 24278689, 2012). "We are currently investigating the mechanisms which mediate the functional roles of TRPM7 and TRPM8 and attempting to develop these ion channels as clinical biomarkers and therapeutic targets for achieving the goal of personalized therapy in pancreatic cancer." (PMID 24278689, 2012). "Although it is unclear how TRPM8 becomes aberrantly expressed in pancreatic adenocarcinoma, current data suggest that TRPM8 plays a functional role in pancreatic tumor by contributing to its uncontrolled growth and progression." (PMID 24278689, 2012).
pancreatic cancer (continued). "Another study also noted evidence suggesting that alterations in TRPM8 N-glycosylation in pancreatic cancer cells play a key role in cell proliferation, with unglycosylated TRPM8 potentially offering protective effects in pancreatic cancer, chiefly attributed to its calcium transport capabilities." (PMID 39062591, 2024). "Abnormal TRPM8 expression gradients have been observed in precancerous pancreatic tissues and malignant tumors, with most pancreatic cancers depicting moderate-to-high TRPM8 levels and a positive correlation noted between anti-TRPM8 immunoreactivity and primary tumor size and stage." (PMID 39062591, 2024). "Finally, the cg19069918 is located near the gene TRPM8, which has been long studied as a cancer biomarker, particularly in pancreatic cancer." (PMID 37587247, 2023). "In addition, future studies are needed to determine the degree of TRPM8 multimerization mediated by LCK is positively correlated with the severity of pancreatic cancer in clinical patients." (PMID 35665750, 2022). "TRPM8 has also been found to be overexpressed in many tumors, including prostate, breast, colorectal, and pancreatic cancers, amongst others, suggesting that TRPM8 may have potential as a marker and drug target for cancer management." (PMID 35847920, 2022). "Importantly, we provided multiple lines of evidence supporting the importance of TRPM8 phosphotyrosine at Y1022 on pancreatic cancer progression in vitro and in vivo." (PMID 35665750, 2022). "Finally, we revealed the importance of TRPM8 phosphorylation at Y1022 in the proliferation, migration, and tumorigenesis of pancreatic cancer cells." (PMID 35665750, 2022). "The first TRPM channel being reported in pancreatic cancer was TRPM8." (PMID 33925979, 2021). "Similarly, in pancreatic cancer cells, siRNA-mediated silencing of TRPM8 enhanced migration, while activation of TRPM8 inhibited migration." (PMID 26512697, 2015). "Taken together with our previously demonstrated role of TRPM8 channels in maintaining proliferation and preventing replicative senescence in pancreatic cancer cells, we propose that the aberrantly expressed TRPM8 plays a contributory role in the growth and metastasis in pancreatic adenocarcinoma." (PMID 24861976, 2014). "The purpose of this paper is to examine the newfound roles of the transient receptor potential (TRP) ion channels, in particular the melastatin subfamily members TRPM7 and TRPM8, in pancreatic cancer and discuss their potential as clinical biomarkers and therapeutic targets." (PMID 24278689, 2012). "However, expression of TRPM8 channels in various pancreatic neoplasms, their clinical significance, and functional roles in pancreatic cancer are mostly unknown." (PMID 24861976, 2014). "Moreover, our data suggest that TRPM8 channels are required for pancreatic cancer cells invasion." (PMID 24861976, 2014). "The TRPM8 inhibitor AMTB is currently under evaluation in early-phase clinical trials for other malignancies, such as pancreatic cancer." (PMID 40869063, 2025). "We next examined the effect of Y1022 in TRPM8 on pancreatic cancer cell proliferation and migration using of RFP-labeled PANC-1 or AsPC-1 cells stably expressing control vector, WT-TRPM8, or mutant TRPM8-Y1022F." (PMID 35665750, 2022). "First, we queried GEPIA to explore the relationship between the TRPV6, TRPA1, TRPM8, TCAF1, and TCAF2 mRNA expressions and sub-stages in pancreatic cancer samples, compared to the control (normal subjects)." (PMID 36012311, 2022). "First, using the GEPIA web platform as a bioinformatic tool, we explored the transcriptional levels of TRPV6, TRPA1, TRPM8, TCAF1, and TCAF2 in pancreatic cancer (n = 179) and normal pancreatic tissues (n = 171)." (PMID 36012311, 2022). "Their identities and functional roles in have recently been discovered in pancreatic cancer; in particular, the transient receptor potential (TRP) channels TRPM7 and TRPM8." (PMID 25770184, 2015).
pancreatic cancer (continued). "With the goal of identifying and developing clinical biomarkers and therapeutic targets in pancreatic cancer, we are actively investigating the mechanistic roles of TRPM7 and TRPM8 ion channels in the initiation, growth, and invasion of pancreatic neoplasia." (PMID 24278689, 2012). "Clinical analysis has further revealed significantly elevated TRPM8 expression levels in pancreatic cancer tissues compared to non-cancerous controls, with augmented TRPM8 expression closely linked to tumor size, advanced TNM stages, and distant metastasis." (PMID 39062591, 2024). "In AsPC-1 and PANC-1 pancreatic cell lines, mutant TRPM8 Y1022F fails to increase cell proliferation and migration, demonstrating the importance of that residue in pancreatic cancer cell proliferation, migration, and tumorigenesis in vitro and in vivo." (PMID 37033630, 2023). "It was demonstrated that pancreatic cancer cells express a non-glycosylated form of TRPM8 channel with biophysical properties different from other cells." (PMID 37033630, 2023). "Our findings demonstrate that the LCK-14-3-3ζ-TRPM8 axis for regulates TRPM8 assembly, channel function, and LCK activity and maybe provide potential therapeutic targets for pancreatic cancer." (PMID 35665750, 2022). "Consistent with the GEPIA results, the expression levels of TRPA1, TRPM8, TCAF1, and TCAF2 were significantly higher in pancreatic cancer tissue (p < 0.001), and TRPV6 expression was significantly lower in pancreatic cancer tissue compared to normal tissues (p < 0.001)." (PMID 36012311, 2022). "We discovered that TRPM8, a nonselective, voltage-gated, and Ca2+ permeable ion channel is aberrantly expressed with a functional role in pancreatic cancer." (PMID 24278689, 2012). "Furthermore, a comparison of 110 pairs of pancreatic cancer tissues and adjacent non-cancerous tissues revealed a correlation of higher expression levels of TRPM8 with worse overall survival and disease-free survival." (PMID 33925979, 2021). "Whether TRPM8 channels play a role in pancreatic cancer cells invasion has not been studied." (PMID 24861976, 2014). "In addition, pancreatic cancer cells lacking TRPM8 showcased diminished proliferation and cell cycle progression capacities alongside heightened cyclin-dependent kinase inhibitor levels, substantiating TRPM8’s indispensable role in cell proliferation within pancreatic adenocarcinoma." (PMID 39062591, 2024).